DICER1 (dicer 1, ribonuclease III)
Diseases named in the same sentence as DICER1 in open-access papers (continued):
Sharing a sentence is not in itself a finding about the gene and the disease.
brain sarcoma (1 paper, 2023). A sarcoma arising from the brain.
cardiomyopathy (1 paper, 2020). A disease of the heart muscle or myocardium proper. "The 21-nt shRNA accumulated at high levels and led to cardiomyopathy, whereas the 19-nt shRNA accumulated at a lower level and was not toxic, likely because the 19-nt shRNA is a less efficient target for Dicer1." (PMID 31927330, 2020).
cervical sarcoma (1 paper, 2023). "Going forward, it may be rational to initially use both “new” and “old” terminology, for example “pulmonary sarcoma with DICER1 alteration (Pleuropulmonary blastoma type III)” or “cervical sarcoma with DICER1 alteration (cervical embryonal rhabdomyosarcoma)”." (PMID 36966138, 2023).
chronic hepatitis B (1 paper, 2023). "Another study found that patients with chronic hepatitis B who had high hepatitis B virus loads had reduced mRNA levels of DROSHA, DICER1, and AGO2 compared with patients with low virus loads." (PMID 37243263, 2023).
colorectal tumors (1 paper, 2018). "Moreover, they observed that primary colorectal tumors with low expression of Dicer1 displayed reduced expression of miR-200s." (PMID 30542509, 2018).
cyst (1 paper, 2025). A sac-like closed membranous structure that may be empty or contain fluid or amorphous material. "In fact, we now test for DICER1 in all patients with lung cyst, especially if they are multi-septated, multiple, or bilateral, symptomatic (shortness of breath and pneumothorax due to cyst rupture) and prenatally unrecognized." (PMID 40069796, 2025).
cystic lung disease (1 paper, 2023). "We presented six children with either proven PPB or DICER1-related cystic lung disease suspected to be PPB, all treated in our hospital within the last 5 years." (PMID 36902703, 2023).
cystic neoplasm (1 paper, 2023). A benign or malignant neoplasm that contains a single or multiple cystic spaces. "LGMT DICER1 mostly represent cystic neoplasms of various organs that usually do not harbor additional molecular alterations and show an excellent clinical outcome." (PMID 36966138, 2023).
diffuse astrocytoma (1 paper, 2018). A low-grade (WHO grade II) astrocytic neoplasm.
ductal carcinoma in situ (1 paper, 2019). "Another study showed the gradual loss of DICER1 protein expression in breast tissues during development of ductal carcinoma in situ (DCIS) and that the most significant reduction was found in metastatic malignant cells." (PMID 31683635, 2019).
embryonic carcinoma (1 paper, 2025). "To investigate the impact of pathogenic hotspot mutations in DICER1-associated tumors, we introduced a hotspot mutation into the endogenous Dicer1 locus of a mouse embryonic carcinoma cell line using CRISPR." (PMID 41188596, 2025). "To model the DICER1-associated tumor genotype in a more physiological setting, we introduced a pathogenic RNase IIIb mutation into the endogenous Dicer1 gene using the P19 cell line, a diploid mouse embryonic carcinoma cell line." (PMID 41188596, 2025).
endocrine cancers (1 paper, 2023). "The presence of DICER1 mutations in endocrine cancers calls for more research given the lack of effective treatments." (PMID 38028548, 2023).
familial isolated pituitary adenoma (1 paper, 2023). "Familial cases represent 5% of PitNEts, which are increasingly recognized as clinicians become more acquainted with familial syndromes, such as familial isolated pituitary adenomas (FIPA), multiple endocrine neoplasia types 1 and 4, X-linked acrogigantism, Carney complex, 3PAs, DICER1, and CABLES1." (PMID 37109772, 2023).
Familial multinodular goiter (1 paper, 2024). "Germline mutations in DICER1 and DGCR8, two of the main miRNA processing genes regulating miRNA maturation, are responsible for the DICER1 and familial multinodular goiter with schwannomatosis syndromes, respectively." (PMID 38252873, 2024).
fibroepithelial polyp (1 paper, 2022). A polypoid lesion composed of fibrous tissue and epithelium. "In this case report, we described a “giant” botryoid fibroepithelial polyp of the parotid duct with DICER1 mutation in an adult female patient." (PMID 34282560, 2022). "In summary, we herein describe the first reported case of a botryoid fibroepithelial polyp occurring within the parotid gland duct and carrying a, likely somatic, pathogenic DICER1 variant." (PMID 34282560, 2022).
fibroma (1 paper, 2023). A non-metastasizing neoplasm arising from the fibrous tissue. "In addition, no FOXL2 nor DICER1 variant has been identified in fibromas." (PMID 38136408, 2023).
gestational diabetes (1 paper, 2020). Carbohydrate intolerance first diagnosed during pregnancy. "Moreover, from these genes, ATG7, DICER1, IGF1R and RANBP2 may play an important role in the genesis and growth of gestational diabetes mellitus and might serve as aberrantly methylation‐based or expression of miRNA‐targeting biomarkers for precise diagnosis and treatment of GDM in the future." (PMID 33085184, 2020).
Hypocalcemia (1 paper, 2021). An abnormally decreased calcium concentration in the blood. "Studies need to be done on whether to recommend total thyroidectomy in carriers of pathogenic germline DICER1 variants, when the diagnosis of a goitre is made, especially as the possible complications of the procedure can be postoperative hypocalcemia and recurrent laryngeal nerve paralysis." (PMID 34552563, 2021).
Hypoglycemia (1 paper, 2009). A decreased concentration of glucose in the blood. "Dicer1-hypomorphic mice were smaller than the wild-type mice before 50 days of age; therefore, we hypothesized that the growth hormone level affects fasting hypoglycemia." (PMID 19148298, 2009). "Thus, the growth hormone level is not responsible for fasting hypoglycemia in Dicer1-hypomorphic mice, probably due to an unknown mechanism involved in glucose metabolism in other tissues." (PMID 19148298, 2009).
kidney cancer (1 paper, 2020). Primary or metastatic malignant neoplasm involving the kidney. "In fact, it wasfound that LINC00847, PTEN and DICER1 are involved inapoptotic pathways in kidney cancer, and interaction network of lncRNAmiRNA- mRNA in RCC wasalso created." (PMID 32779439, 2020). "Enrichr was used to analyze GObiological process in order to further study biological effects of aberrantly-expressedPTEN and DICER1 in kidney cancer." (PMID 32779439, 2020).
learning disabilities (1 paper, 2023). "The patient subsequently manifested growth retardation (-2DS) and learning disabilities leading to genetic explorations and the identification of a germline pathogenic DICER1 variant." (PMID 37215607, 2023).
Leydig cell ovarian tumor (1 paper, 2024). "We presented a rare clinical case of an early-stage moderately differentiated unilateral DICER1 wild-type Sertoli–Leydig cell ovarian tumor with AFP elevation that caused amenorrhea in an adolescent patient." (PMID 39336518, 2024).
lymphocytic thyroiditis (1 paper, 2025). "DICER1 positivity was also very intense (3 +) in the germinal centers of lymphocytic thyroiditis." (PMID 40448797, 2025).
malignant teratoma (1 paper, 2020). A malignant form of teratoma. "On the other hand, the so-called malignant teratomas affect predominantly adults and elderly, are highly aggressive, and, according to a few published cases, harbor DICER1 mutations." (PMID 32507920, 2020).
medullary thyroid cancer (1 paper, 2020). "Furthermore, it was observed that MNG1 corresponded to DICER1 gene, related to microRNA biogenesis (described in “Syndromic causes of non-medullary thyroid cancer” section)." (PMID 33218058, 2020).
mesenchymal neoplasms (1 paper, 2023). "Here we identify a group of mesenchymal tumors which is highly associated with DICER1 syndrome, and molecularly distinct from other DICER1-associated tumors." (PMID 36966138, 2023). "Here, the authors identify and characterize 3 molecular subgroups of mesenchymal tumors with DICER1 mutations." (PMID 36966138, 2023). "It is tempting to suggest that the development of DICER1-associated mesenchymal tumors at a specific anatomical location represents a disease continuum with transition from cystic to sarcomatous configuration." (PMID 36966138, 2023). "LGMT DICER1, SARC DICER1 and PIS DICER1 represent a group of mesenchymal neoplasms with DICER1 alterations, which are distinct from other DICER1-associated tumors." (PMID 36966138, 2023). "Available survival data suggested differences between the three groups of mesenchymal tumors with DICER1 alteration, with a significantly better progression free survival for LGMT DICER1 when compared to SARC DICER1 and PIS DICER1." (PMID 36966138, 2023). "We consider that it would be desirable to implement the herein proposed nomenclature for mesenchymal tumors with DICER1 alteration." (PMID 36966138, 2023). "We also show that some other DICER1-associated lesions, such as SLCT DICER1, nodular thyroid lesions (MG and PCA), PINB, MEPL and WILMS correspond to molecular classes distinct from the classes of DICER1-associated mesenchymal tumors." (PMID 36966138, 2023). "Here, we address this hypothesis by analyzing 534 tumors, including a large number with DICER1 PVs, by DNA methylation profiling and identify three classes of mesenchymal tumors with DICER1 alteration, comprising tumors from various anatomical locations." (PMID 36966138, 2023). "In conclusion, we demonstrate that mesenchymal tumors with DICER1 alteration comprise three distinct clinicopathological and molecular tumor classes, which may warrant a change in nomenclature." (PMID 36966138, 2023). "Our study not only provides a combined approach to classify DICER1-associated neoplasms for improved clinical management but also suggests a role for global hypomethylation and other recurrent molecular events in sarcomatous differentiation in mesenchymal tumors with DICER1 alteration." (PMID 36966138, 2023). "Nevertheless, further studies into the cellular origins of mesenchymal tumors with DICER1 alteration are needed to expand on our hypothesis." (PMID 36966138, 2023). "Our results similarly show that in mesenchymal tumors with DICER1 alterations DNA hypomethylation is correlated with chromosomal instability and, more specifically, that regions affected by chromosomal gains may especially be prone to be hypomethylated." (PMID 36966138, 2023). "The presence of an overtly sarcomatous differentiation (LGMT DICER1 vs. SARC DICER1), anatomical location (SARC DICER1 vs. PIS DICER1) and the identification of a DICER1 hotspot PV, will usually be sufficient to classify DICER1-associated mesenchymal neoplasms." (PMID 36966138, 2023). "In this study, we identify a group of mesenchymal tumors with DICER1 alteration, which includes three classes termed LGMT DICER1, SARC DICER1 and PIS DICER1." (PMID 36966138, 2023). "These three tumor classes comprise mesenchymal tumors of various anatomical locations that typically harbor a combination of a DICER1 LOF PV alongside a DICER1 missense PV (non-classic two hit tumor suppressor PVs)." (PMID 36966138, 2023).
microcephaly (1 paper, 2022). A congenital or acquired developmental disorder in which the circumference of the head is smaller than normal for the person's age and sex. "Conditional knockout of Dicer1 in excitatory forebrain neurons of mice led to microcephaly, reduced dendritic branch elaboration, and increased dendritic spine length in the brain." (PMID 35743796, 2022).
mucoepidermoid carcinoma (1 paper, 2015). A carcinoma morphologically characterized the presence of cuboidal mucous cells, goblet-like mucous cells, squamoid cells, cystic changes, and a fibrotic stromal formation. "A study describing the expression of Dicer1 in mucoepidermoid carcinoma found that Dicer1 was expressed higher in MEC compared to surrounding normal tissue." (PMID 26544193, 2015).
myeloid neoplasm (1 paper, 2025). Proliferation of myeloid cells originating from a primitive stem cell. "DICER1 and DROSHA transcripts showed a consistent and statistically significant reduction in both AML and MDS compared with controls (p < 0.05), suggesting global downregulation of the early miRNA-processing machinery in myeloid malignancies." (PMID 41463093, 2025).
non-epithelial ovarian cancer (1 paper, 2014). "More recently, recurrent somatic mutations of DICER1 around metal-binding residues were found in non-epithelial ovarian cancer." (PMID 24362839, 2014).
non-small cell lung adenocarcinoma (1 paper, 2023). Type of epithelial lung cancer arising from glandular origin. "Finally, he was diagnosed with non-small cell lung adenocarcinoma at the age of 44 years with a positive DICER1 test." (PMID 37509342, 2023).
nonalcoholic fatty liver disease (1 paper, 2021). "Through further research, they found that serum lipid disorder caused by Dicer1 deletion may be due to the decreased expression of miR-29, which improves nonalcoholic fatty liver disease by suppressing HMGCR expression." (PMID 34099844, 2021).
ovarian adenocarcinoma (1 paper, 2018). An adenocarcinoma that arises from the ovary. "While this is not a DICER1 hotspot mutation, the position is just a few amino acids away from the catalytic site and three cases have been described to be mutated at this position in the COSMIC and TCGA datasets (one colon and two ovarian adenocarcinoma, all E1803K substitutions)." (PMID 29492199, 2018).
ovarian germ cell tumor (1 paper, 2018). A neoplasm that arises from the ovary and originates from germ cells. "This mutation is known to cause a loss of negative charge in the magnesium-binding pocket of the RNAse IIIb domain of both the murine Dicer1 and human DICER1 protein and has been reported as recurrent mutation in ovarian germ cell tumors." (PMID 29492199, 2018).
pituitary disease (1 paper, 2018). "Endocrine follow-up of patients carrying DICER1 mutations should consider pituitary disease." (PMID 30306785, 2018).
pituitary tumour (1 paper, 2018). "Despite its small sample size of 12, this study strongly proposes the link between DICER1 mutations and the development of a pituitary tumour." (PMID 30306785, 2018).
primitive neuroectodermal tumor (1 paper, 2020). A malignant neoplasm that originates in the neuroectoderm. "Poorly differentiated ovarian sarcoma, retiform SLCT, and primitive neuroectodermal tumor (PNET) of the cervix have also been reported in individuals with possible germline DICER1 variants." (PMID 33552988, 2020).
rectum adenocarcinoma (1 paper, 2019). An adenocarcinoma arising from the rectum. "A single participant with a uterine corpus endometrial carcinoma harbored two pathogenic germline DICER1 (hotspot and splice‐donor) variants, and a single participant with a rectal adenocarcinoma harbored a germline DICER1 stop‐gained variant." (PMID 30672147, 2019). "Using a more stringent calculation by only considering P variants, the prevalence of DICER1 P was ~1:4,600 (one subject with rectum adenocarcinoma and one subject with uterine corpus endometrial carcinoma)." (PMID 30672147, 2019). "In TCGA data, we observed germline pathogenic DICER1 variation in one rectal adenocarcinoma." (PMID 30672147, 2019). "The rectum adenocarcinoma occurred in a 62‐year‐old female with a truncating DICER1 variant; we did not observe any somatic P/LP DICER1 variation in the associated tumor." (PMID 30672147, 2019).
retinal diseases (1 paper, 2020). "GA, unlike many other retinal diseases, is associated with a decreased expression of DICER1 in retinal pigment epithelium (RPE) cells." (PMID 32765950, 2020).
rhabdoid tumor (1 paper, 2025). An aggressive malignant embryonal neoplasm usually occurring during childhood. "Non-epithelial tumors may occur in specific hereditary contexts such as DICER1 mutations, Peutz–Jeghers syndrome, or rhabdoid tumor predisposition." (PMID 41170462, 2025).
rheumatic disease (1 paper, 2019). "One study found that the anti-Su autoantibodies from rheumatic patients' sera were capable of immunoprecipitating DICER1 protein, indicating its implication in rheumatic diseases." (PMID 31275058, 2019). "However, the possible implication of DICER1 in rheumatic disease has been long left unknown." (PMID 31275058, 2019).
sellar tumor (1 paper, 2023). "Such information prompted further evaluation of the relationship among these two samples and the rare, DICER1-associated sellar tumor known as pituitary blastoma that exclusively occurs in children younger than 2 years." (PMID 37835574, 2023).
Sepsis (1 paper, 2020). Sepsis is defined as life-threatening organ dysfunction caused by a dysregulated host response to infection. "Sepsis-reduced miR-26b was further studied using Dicer1 siRNA and calpain inhibition in MEG-01 cells." (PMID 32013235, 2020).
Sertoli cell tumor (1 paper, 2023). A sex cord-stromal tumor of the testis or the ovary. "A DICER1 variant has been identified in 63% of pure Sertoli cell tumors." (PMID 38136408, 2023). "Therefore, the identification of DICER1 variant is not mandatory to make the diagnosis of Sertoli cell tumor." (PMID 38136408, 2023). "The identification of a DICER1 variant could be helpful to differentiate SCTAT with Sertoli cell tumor-like areas (no DICER1 variant,) from Sertoli cell tumor with minor SCTAT component (DICER1 variant in 63% of the cases)." (PMID 38136408, 2023).
spinal muscular atrophy (1 paper, 2015). A motor neuron disease that affect the muscles, and characterized by muscle weakness and atrophy resulting from progressive degeneration and irreversible loss of the anterior horn cells in the spinal cord (i.e., lower motor neurons) and the brain stem nuclei. "Dicer1 deletion in spinal motor neurons results in a spinal muscular atrophy (SMA)-like phenotype." (PMID 26437437, 2015).
squamous cell carcinoma of the esophagus (1 paper, 2008). "DICER1 expression varies in squamous cell carcinoma of the esophagus and does not show significant association with patient survival." (PMID 19578509, 2008).
Stillbirth (1 paper, 2023). Death of the fetus in utero after at least 22 weeks of gestation. "Though we identified a de novo frameshift SNV in stillbirth, other polymorphisms in DICER1 were previously shown to be associated with spontaneous miscarriage before 20 weeks’ gestation and recurrent pregnancy loss before 14 weeks’ gestation." (PMID 36800380, 2023).
Thyroid adenoma (1 paper, 2025). The presence of a adenoma of the thyroid gland. "The same DICER1 (c.4068_4069delGT, p(Tyr1357fs*18) constitutional pathogenic variant was identified in the “normal” thyroid tissue (variant allele frequency [VAF]: 51%), the main nodule (VAF: 50%), and the thyroid adenoma (VAF: 52%)." (PMID 40892116, 2025).
tonsillar cancers (1 paper, 2016). "Subsequent QRT-PCR measurement of Drosha, Dicer1, DDX5 and DGCR8 indicated a general overexpression of all four biogenesis components in tonsillar cancers." (PMID 26867589, 2016).
undifferentiated sarcoma (1 paper, 2026). "DICER1 syndrome was present in three patients (3/158, 1.9%), two having an anaplastic sarcoma of the kidney and one an undifferentiated sarcoma (p = 0.0003)." (PMID 41509607, 2026).
urothelial carcinoma (1 paper, 2022). A malignant neoplasm derived from the transitional epithelium of the urinary tract (urinary bladder, ureter, urethra, or renal pelvis). "Interestingly, targeted sequencing identified four mutations shared by all of the tissue samples, including the urothelial carcinoma: BRCA1 p.Val340GlyfsTer6, DICER1 p.Arg490His, IRS2 p.Arg744Cys, and PDGFRB p.Arg853Trp." (PMID 35260767, 2022).